SOX12 (SRY-box transcription factor 12)
Diseases named in the same sentence as SOX12 in open-access papers (continued):
Sharing a sentence is not in itself a finding about the gene and the disease.
lymph node metastasis (2 papers, 2019 to 2022). "SOX12 overexpression was significantly associated with tumor invasion, tumor differentiation, lymph node metastasis, distant metastasis, and American Joint Committee on Cancer (AJCC) staging, and was found to be an independent risk factor for reduced survival and recurrence in patients." (PMID 30858360, 2019).
osteosarcoma (2 papers, 2021 to 2022). A usually aggressive malignant bone-forming mesenchymal neoplasm, predominantly affecting adolescents and young adults. "To explore the relationship between SOX12 expression and osteosarcoma prognosis or recurrence, we analyzed the GSE21257 database and observed that SOX12 elevated expression indicated a poor prognosis for patients with osteosarcoma." (PMID 34725550, 2021). "In this study, we observed that SOX12 promoted stem cell-like phenotypes and osteosarcoma tumor growth by upregulating JAGGED1." (PMID 34725550, 2021). "SOX12 expression was increased in osteosarcoma; high SOX12 expression levels were related to a poor prognosis and a high disease recurrence in patients." (PMID 34725550, 2021). "When compared with ordinary osteosarcoma cells, SOX12 expression in osteosarcoma cancer stem cells was increased." (PMID 34725550, 2021). "SOX12 expression in osteosarcoma cells transfected with shRNA-SOX12 was downregulated when compared with cells transfected with shRNA-NC." (PMID 34725550, 2021). "In our study, we observed that SOX12 promoted stem cell-like phenotypes and osteosarcoma tumor growth by upregulating JAGGED1." (PMID 34725550, 2021). "SOX12 expression was highly regulated in the osteosarcoma cell lines, U2OS, SAOS2, 143B, and MG63, when compared with human osteoblasts, hFOB." (PMID 34725550, 2021). "Our most important finding for our study was that SOX12 was highly expressed in osteosarcoma, and this high expression was related to a poor prognosis and high disease recurrence in osteosarcoma patients." (PMID 34725550, 2021). "We also observed that SOX12 knockdown inhibited the spheroidization and expression of stemness markers in osteosarcoma cells and tumor formation in nude mice." (PMID 34725550, 2021). "From the TARGET database, patients with osteosarcoma expressing high SOX12 levels had higher disease recurrence rates." (PMID 34725550, 2021). "We also performed in vitro and in vivo assays to determine SOX12 function in osteosarcoma etiology." (PMID 34725550, 2021). "Finally, we have shown that SOX12 promotes stem cell-like phenotypes and osteosarcoma tumor growth by upregulating JAGGED1." (PMID 34725550, 2021). "Furthermore, SOX12 expression in osteosarcoma cell lines was higher than normal bone tissue in the GSE42352 database." (PMID 34725550, 2021). "SOX12 plays a role in promoting the growth of some tumors; however, its role in osteosarcoma remains unclear." (PMID 34725550, 2021). "After SOX12 knockdown, the spheroidization ability of osteosarcoma cells was decreased." (PMID 34725550, 2021). "SOX12 promotes stem cell-like phenotypes and osteosarcoma tumor growth by upregulating JAGGED1." (PMID 34725550, 2021). "From gene expression omnibus (GEO) and tumor alterations relevant for genomics-driven therapy (TARGET) databases, Kaplan–Meier analyses were conducted to establish relationships between SOX12 expression and osteosarcoma survival and recurrence in osteosarcoma patients." (PMID 34725550, 2021). "Moreover, SOX12 expression in osteosarcoma cell lines was increased, similar to osteosarcoma cancer stem cells." (PMID 34725550, 2021). "After that, we conducted tumor stemness-related assays, and we found that the osteosarcoma cells overexpressing SOX12 are more capable of forming spheres than the control, and the stemness markers of the 143B cells overexpressing SOX12 are higher than that of the control group." (PMID 34725550, 2021). "However, the precise role of SOX12 in osteosarcoma remains unknown." (PMID 34725550, 2021). "Finally, during SOX12 knockdown, JAGGED1 overexpression rescued osteosarcoma cells from spheroidizing." (PMID 34725550, 2021). "Similarly, from the GSE28424 database, SOX12 expression in osteosarcoma patients was higher than in nonosteosarcoma patients." (PMID 34725550, 2021).
osteosarcoma (continued). "These cells can be enriched in sphere cultures under the conditions of osteosarcoma stem cell culture; we grew two osteosarcoma cell lines 143B and U2OS under sphere culture conditions to enrich CSCs, and then, we detect osteosarcoma the expression of SOX12 in stem cells and ordinary cells." (PMID 34725550, 2021).
thyroid cancer (2 papers, 2025). "We then used immunohistochemical analysis to evaluate the expression levels of SOX12, YBX1 and LDHA in thyroid cancer tissues with different expression levels of SOX12." (PMID 40593465, 2025). "In the context of thyroid cancer, SOX12 was reported to promote thyroid cancer invasion through interactions with the POU family." (PMID 40593465, 2025). "We integrated several thyroid cancer single-cell sequencing (scRNA-seq) datasets to investigate the importance of SOX12 transcripts during thyroid cancer (TC) progression (GSE148673, GSE184362, and GSE134355)." (PMID 40593465, 2025). "To investigate the role of SOX12 in thyroid cancer, we examined SOX12 levels in thyroid cancer cells and found that SOX12 was expressed at much higher levels in thyroid cancer cell lines than in normal human thyroid follicular epithelial cells (Nthy-ori 3-1)." (PMID 40593465, 2025). "The transcriptional regulation of LDHA by SOX12 encouraged us to determine whether LDHA was a functional downstream target of SOX12 during its promotion of thyroid cancer metastasis." (PMID 40593465, 2025). "We further investigated whether SOX12 regulated the migration and invasion of thyroid cancer cells by regulating LDHA expression." (PMID 40593465, 2025). "In thyroid cancer, NR2F1-AS1 promotes proliferation and inhibits apoptosis via the miR-338-3p/CCND1 and miR-423-5p/SOX12 pathways." (PMID 40828427, 2025). "In thyroid cancer, its migratory function is executed through similar ceRNA interactions, targeting miR-338-3p/CCND1 and miR-423-5p/SOX12." (PMID 40828427, 2025). "However, as a transcription factor, the epigenetic regulatory role of SOX12 in thyroid cancer progression has not yet been reported." (PMID 40593465, 2025).
bladder cancer (1 paper, 2021). "SOX12 mutation mainly occurred in bladder cancer with a hot spot of E294K, but there were a few comparable differences with the other cancer types." (PMID 34442467, 2021).
colon adenocarcinoma (1 paper, 2014). "Data mining from public platforms revealed that the mRNA levels of TMED3, but not of SOX12, increased in colon adenocarcinoma versus matched normal colon tissue." (PMID 24920608, 2014).
epilepsy (1 paper, 2024). A brain disorder characterized by episodes of abnormally increased neuronal discharge resulting in transient episodes of sensory or motor neurological dysfunction, or psychic dysfunction. "Furthermore, our investigation seeks to address this gap in the literature by exploring the potential involvement of SOX12 in neurodevelopmental processes, thus laying the groundwork for future research into the diverse array of genes implicated in epilepsy and neurodevelopmental disorders." (PMID 39057025, 2024). "In this study, we aim to establish a potential link between a de novo variant identified within the SOX12 gene through WES and epilepsy, diagnosed in the patient under examination." (PMID 39057025, 2024).
mantle cell lymphoma (1 paper, 2010). Mantle cell lymphoma is a rare form of malignant non-Hodgkin lymphoma affecting B lymphocytes in the lymph nodes in a region called the ``mantle zone''. "In this study we found variable expression of SOX11, SOX4 and SOX12 mRNA in mantle cell lymphoma cell lines." (PMID 21124928, 2010).
multiple myeloma (1 paper, 2023). "miR-744-5p inhibited multiple myeloma proliferation by targeting the SOX12/Wnt/β-catenin pathway, and inhibited the proliferation and metastasis of HCC by targeting TGF-β1." (PMID 36922987, 2023).
osteoporosis (1 paper, 2024). A condition of reduced bone mass, with decreased cortical thickness and a decrease in the number and size of the trabeculae of cancellous bone (but normal chemical composition), resulting in increased fracture incidence. "The SOX4, SOX11 and SOX12 (SOXC) transcription factors were previously shown to control many developmental processes, including skeletogenesis, and SOX4 was linked to osteoporosis, but how SOXC control adult bone mass remains unknown." (PMID 38580651, 2024).
tongue squamous cell carcinoma (1 paper, 2020). A squamous cell carcinoma that arises from the tongue. "LncRNA CASC9 is upregulated in tongue squamous cell carcinoma tissues and cells, suggesting that patients have poor prognosis and can influence the malignant process of tongue squamous cell carcinoma by regulating the miR‐423‐5p/SOX12 axis." (PMID 33174687, 2020).
viral infection (1 paper, 2020). "HCC patients under viral infection or alcohol intake with increased SOX12 expression had poorer prognosis." (PMID 32184801, 2020). "And HCC patients under viral infection or alcohol intake with increased SOX12 expression had poorer prognosis." (PMID 32184801, 2020). "Interestingly, we find that increased SOX12 expression can impact the prognosis of male HCC patients, and patients with viral infection and alcohol intake." (PMID 32184801, 2020).
tumor (31 papers, 2014 to 2025). "In the TCGA-STAD and GTEX cohorts, the expression of SOX12 was significantly associated with overall survival and higher in tumor tissues than in normal tissues or tumor-adjacent normal tissues across different cancer types." (PMID 40593465, 2025). "Overexpression of SOX12 was associated with a loss of tumor capsule." (PMID 35884444, 2022). "The overexpressed SOX12 is associated with tumor encapsulation, microvascular invasion, higher TNM stage, and poor prognosis of HCC cases, suggesting that SOX12 could be an independent risk factor for recurrence and worse survival." (PMID 35267473, 2022). "Downregulation of GLS, GOT2, and ASNS effectively blocks SOX12-mediated CRC cell proliferation and metastasis, while ectopic expression of these enzymes reverses the inhibitory effects of SOX12 knockdown on tumor progression." (PMID 40842990, 2025). "It has been reported that SOX12 helps in maintaining the tumor characteristics of HCC and induces tumor metastasis through the EMT process in HCC." (PMID 40593465, 2025). "For example, SOX12, a tumour metastasis-promoting factor, promotes the formation of aspartic acid and eventually leads to tumour metastasis by upregulating various glutamine metabolic enzymes, including GOT2." (PMID 37829798, 2023). "UCHL3-medicated tumor growth was significantly decreased by SOX12 knockdown, indicating the function of SOX12 in CRC." (PMID 37280524, 2023). "SOX12, a direct target of miR-370, attenuates miR-370-mediated tumor suppression through up-regulation." (PMID 35743814, 2022). "Over the past few years, increasing research has demonstrated the crucial role of SOX12 in tumor occurrence, growth, proliferation, invasion, and metastasis, with different biological behaviors in different types of tumors." (PMID 36120594, 2022). "SOX12 (Sex-determining region Y-box12) is a transcription factor, its upregulation promotes tumor progression and it is involved in EMT, apoptosis and cell proliferation." (PMID 35954418, 2022). "miR-370 mediates fatty acid oxidation by targeting SOX12, limiting cancer cell proliferation, migration and invasion, and ultimately blocking tumor metastasis." (PMID 35743814, 2022). "The results showed that the expression of SOX12 was upregulated in OC tumor tissues and cells compared with non-tumor tissues and cells." (PMID 34789303, 2021). "SOX12 played an important role in tumor proliferation and metastasis and was increased in different types of cancers (from TCGA database, data not shown)." (PMID 34745940, 2021). "miR-544-5p expression was decreased, while SOX12 expression was increased in OC tumor tissues and cells." (PMID 34789303, 2021). "Based on the predicted results and RT-qPCR results, we found SOX12 is a target gene of miR-744-5p, and the expression was increased in OC tumor tissues and cells." (PMID 34789303, 2021). "IHC staining for Ki67 in the xenografts revealed significant increases in the proliferation of tumor cells overexpressing SOX12." (PMID 30858360, 2019). "A subcutaneous xenograft nude mice model was established for tumorigenesis and the results showed that SOX12 overexpression significantly increased tumor growth, whereas SOX12 inhibition suppressed tumor growth." (PMID 30858360, 2019). "The knockout of GOT2 weakens SOX12-induced tumour metastasis." (PMID 37829798, 2023). "GOT2 overexpression weakens the inhibition of tumour metastasis by SOX12 knockdown." (PMID 37829798, 2023). "SOX12, one of the sex-determining region Y-associated high-mobility group (HMG) cassette (SOX) family genes, and its overexpression has been associated with the promotion of tumor progression and poor prognosis in CRC." (PMID 36090030, 2022). "Consistently, our study revealed that SOX12 was over-expressed in OS tumor tissues." (PMID 36266695, 2022). "Reportedly, SOX12 is a tumor-promoting gene in hepatocellular cancer and breast carcinoma." (PMID 36120594, 2022).
tumor (continued). "SOX12 is a novel marker for liver CSCs and is related to tumor metastasis." (PMID 35267473, 2022). "We found that miR-125b-5p could bind to the 3′-UTR region of SOX12, which is a key gene that promotes tumor metastasis." (PMID 34745940, 2021). "Then, we detected SOX12 expression in OC tumor tissues and cells by RT-qPCR." (PMID 34789303, 2021). "Our data revealed that SOX6 and SOX12 might play a specific role in the immunosuppressive tumor microenvironment by regulating regulatory T cells (Tregs)." (PMID 34868396, 2021). "Finally, we found that the SOX6 and SOX12 expression levels were correlated with tumor-infiltrating immune cells (TIICs)." (PMID 34868396, 2021). "The results were consistent with what was reported in the literature, indicating that SOX6 may serve as a tumor suppressor, while SOX12 may serve as an oncogene in ccRCC." (PMID 34868396, 2021). "Administration of l-asparaginase decreased SOX12-mediated tumor growth and metastasis." (PMID 30858360, 2019). "ASNS, GLS, and GOT2 encode ASNS, GLS, and GOT2, respectively, which are key enzymes in asparagine synthesis and are all required for tumor growth and metastasis, prompting the hypothesis that asparagine synthesis is required for SOX12-mediated CRC progression." (PMID 30858360, 2019). "Interestingly, SOX12 has been reported to promote tumor progression and datasets from the Cancer Genome Atlas (TCGA) indicate that SOX12 upregulation is correlated with poor prognosis in multiple types of cancer, including CRC." (PMID 30858360, 2019). "Silencing of PD-L1 efficiently boosted the anti-tumor effect of cetuximab on cell proliferation and apoptosis, additionally, these effects mediated by PD-L1 knockdown could be counteracted by SOX12 upregulation." (PMID 40592832, 2025). "Therefore, it is accepted that SOX12 plays key roles in many tumor types and some tumor stem cells." (PMID 34725550, 2021). "Therefore, HCSCs markers likely play an important role in tumor related immune infiltration and SOX12 might be a potential therapeutic target in patients with HCC." (PMID 32184801, 2020). "To test whether knockdown of TMED3 or SOX12 could promote full metastasis from a primary tumor to a distant organ, we subcutaneously grafted CC14 lacZ+ cells expressing pSIH lentivectors into nude mice and scored for the presence of βgal+ colonies in the lungs." (PMID 24920608, 2014). "The results revealed significantly higher SOX12 expression in tumor tissues than in normal tissues, and the expression levels of YBX1 and LDHA were consistent with those of SOX12." (PMID 40593465, 2025). "The TF SOX12, which shows increased expression in THCA tissue and cells compared to normal thyroid, promotes cell proliferation, migration, invasion, and tumor growth and has been reported to interact with members of the POU family." (PMID 39226186, 2024). "Cox regression analyses were performed to identify independent clinical prognostic parameters to construct a combined nomogram which includes the expression of CERCAM, MIA2, HS6ST2, ONECUT2, SOX12, TMEM132A, pT stage, tumor size and ISUP grade." (PMID 35954418, 2022). "SOX12 is a member of the SOX gene family and plays important roles in various biological processes, including tumor cell differentiation and immunity." (PMID 34725550, 2021). "The expression of SOX12 was higher in the tumor cell subgroup compared to normal subgroup, whereas other SOX transcripts, including SOX2, SOX5, SOX9, SOX11, and SOX15, had low expression in tumor clusters." (PMID 40593465, 2025). "Given the vital role of CCL22 and its receptor CCR4 on Tregs recruitment and tumor progression, we hypothesized that CCL22‐CCR4 axis was involved in SOX12‐induced Tregs enrichment." (PMID 39072947, 2024).
tumor (continued). "In this model, the results we obtained were consistent with those indicated in the hepatocyte‐specific SOX12 knockout model established using the AAV8‐TBG‐Cre system, demonstrating a remission of DEN/CCl4‐induced tumor burden, mouse mortality, lung metastasis, and impaired liver function." (PMID 39072947, 2024). "Specifically, SOX12 transactivated CCL22, which resulted in the accumulation and enhanced activity of CCR4+Tregs within the tumor, whereas SOX18 up‐regulated CXCL12 expression, attracting CXCR4+TAMs and CXCR4+Tregs into the tumor." (PMID 39072947, 2024). "In addition, downregulation of ASNS, inhibited SOX12-mediated CRC cell proliferation and metastasis in tumor cells overexpressing SOX12." (PMID 36090030, 2022). "In vivo tumorigenesis experiments revealed significant decreases in tumor growth, tumor weight, and Ki67-positive staining upon silencing of GLS, GOT2, or ASNS in SW480-SOX12 cells, whereas GLS, GOT2, or ASNS overexpression reversed the SOX12 knockdown-induced suppression of tumor growth." (PMID 30858360, 2019). "During CRC development, HIF-1α binds to the SOX12 (SRY-box transcription factor 12) promoter to increase SOX12 expression, which further increases the SOX12-mediated expression of GLS and GOT2, leading to cellular metabolism adaptation that promotes tumor progression." (PMID 36755301, 2023). "Moreover, we confirmed a negative correlation between the expression of SOX12 and miR-744-5p in OC tumor tissues." (PMID 34789303, 2021). "Patients with positive SOX12, Foxp3, CD11b, and CD163 expression or negative CD8 expression showed tumor‐aggressive tendency and poor prognosis." (PMID 39072947, 2024). "Both TMED3 and SOX12 repress metastatic growth in the lungs, but only TMED3 also suppresses full metastasis from primary tumors, and this is not due to a simple enhancement of tumor growth." (PMID 24920608, 2014).